IGFBP7 (insulin like growth factor binding protein 7)
Diseases named in the same sentence as IGFBP7 in open-access papers (continued):
Sharing a sentence is not in itself a finding about the gene and the disease.
hepatopulmonary syndrome (1 paper, 2025). Hepatopulmonary syndrome (HPS) is a lung disease characterized by widening of arteries and veins (dilatation) in the lungs in people who have chronic liver disease. "IGFBP-7 appears to be particularly specific for PAH associated with hepatopulmonary syndrome and may serve as a marker of vascular remodeling in this subgroup." (PMID 41169887, 2025). "Notably, IGFBP-7 is markedly elevated in hepatopulmonary syndrome-associated PAH and strongly correlates with clinical outcomes." (PMID 41169887, 2025).
hydatidiform mole (1 paper, 2024). A gestational trophoblastic disorder characterized by marked enlargement of the chorionic villi, hyperplasia of the villous trophoblastic cells and hydropic changes. "IHC analysis revealed that downregulation of IGFBP7 may play a significant role in the progression of complete hydatidiform mole." (PMID 39081862, 2024).
hypertensive retinopathy (1 paper, 2020). Retinopathy due to hypertension. "IGFBP7 has been linked to hypertensive retinopathy and familial retinal macroaneurysms, indicating its role in retinal vascular pathology." (PMID 33217969, 2020).
hypothyroidism (1 paper, 2023). Abnormally low levels of thyroid hormone. "Multiple RAMs, on the other hand, had been recorded in young patients homozygous for the retinal arterial macroaneurysms with supravalvular pulmonic stenosis (RAMSVPS) syndrome causative IGFBP7 variant, two of whom had an associated hypothyroidism." (PMID 37165392, 2023).
kidney transplant (1 paper, 2017). A surgical procedure in which one or both kidneys from a donor are implanted into a recipient. "We collected urine samples of 33 kidney transplant recipients and 14 non-transplanted patients who all had AKI (stages 1–3 according to KDIGO), and measured [IGFBP7]x[TIMP-2] using the NephroCheck® Astute1 40 TM meter." (PMID 29145491, 2017).
laryngeal carcinoma (1 paper, 2024). Carcinoma that arises from the laryngeal epithelium. "A detailed understanding of the function and importance of IGFBP7 and ANXA1 may help to further elucidate the biological mechanisms of laryngeal carcinoma and support the development of early diagnosis and preventive treatment." (PMID 38893148, 2024).
Left atrial enlargement (1 paper, 2024). Increase in size of the left atrium. "Sacubitril/valsartan treatment reduced IGFBP7 levels, suggesting its involvement in HFpEF pathophysiology, particularly diastolic dysfunction and left atrial enlargement." (PMID 38255264, 2024).
left ventricular hypertrophy (1 paper, 2022). Enlargement of the LEFT VENTRICLE of the heart. "Increased heart weight normalized with tibia length (HW/TL), a key indicator of left ventricular hypertrophy, and increased lung weight, a sign of congestive HF, were observed in WT mice but not in Igfbp7−/− mice after TAC surgery." (PMID 39196168, 2022).
limb ischemia (1 paper, 2016). A ischemia that involves the limb. "The mechanisms responsible for this effect are still unclear, but we have proposed that limb ischemia releases damage-associated molecular patterns that signal the kidney to release TIMP-2 and IGFBP7 as part of an “alarm” that protects cells from subsequent injury." (PMID 27245788, 2016).
liver cirrhosis (1 paper, 2018). "The studies on animal models have also greatly contributed to our understanding of the role of less known IGF system components, e.g. IGFBPrP1 (IGFBP7), in the pathogenesis of liver cirrhosis." (PMID 29702590, 2018).
liver disease (1 paper, 2019). "However, despite negative result, this is the first study testing the usefulness of urine [TIMP-2]·[IGFBP7] as an early biomarker of AKI in advanced liver disease patients." (PMID 31601879, 2019).
lymphopenia (1 paper, 2022). Reduction in the number of lymphocytes. "We first investigated the association of IGFBP7 − AS1 and IGFBP7 expression with six subtypes of immune infiltration: C1 (wound healing), C2 (INF-r dominant), C3 (inflammation), C4 (lymphopenia dominant), C5 (immunologically quiet), and C6 (TGFβ dominant)." (PMID 35836132, 2022).
malaria (1 paper, 2020). Malaria is a serious and sometimes fatal disease caused by a parasite that commonly infects a certain type of mosquito which feeds on humans. "It is hoped that future clinical studies will investigate associations between IGFBP7 and malaria pathogenesis and immunity." (PMID 32066522, 2020). "Functionally, we observed that the IGFBP7-mediated type II rosetting reduced phagocytosis by monocytes, and therefore defined a new escape mechanism for the malaria parasites." (PMID 32066522, 2020). "It would be interesting to compare the serum/plasma IGFBP7 levels of uncomplicated and severe malaria patients from the same area to understand better the role of IGFBP7 in malaria pathogenesis." (PMID 32066522, 2020).
memory impairment (1 paper, 2020). "Changes in IGFBP-7 levels have been correlated with postoperative cognitive dysfunction and AD-like memory impairments." (PMID 32191705, 2020).
metastatic tumours (1 paper, 2024). "In another STAD dataset, GSE35809, IGFBP7 was found to be overexpressed in invasive tumours compared with in proliferative and metastatic tumours." (PMID 39351597, 2024).
nevus (1 paper, 2020). Nevus (or naevus, plural nevi or naevi, from nævus, Latin for "birthmark") is the medical term for sharply circumscribed[1] and chronic lesions of the skin or mucosa. "For example, we observed that the vast majority of Igfbp7 transcripts are produced by fibroblasts and endothelial cells and that, among melanocytes, nevus melanocytes express lower levels of Igfbp7 than non-nevus melanocytes." (PMID 33047672, 2020).
non-alcoholic fatty liver disease (1 paper, 2024). "In contrast, increased expression of IGFBP7 has been observed in patients with non-alcoholic fatty liver disease (NAFLD), which could be reproduced in a zebrafish model." (PMID 39045455, 2024).
osteosarcoma (1 paper, 2026). A usually aggressive malignant bone-forming mesenchymal neoplasm, predominantly affecting adolescents and young adults. "We showed that the editing activity of ADAR2 on IGFBP7 abolishes its proliferative effect on osteosarcoma cells and triggers terminal differentiation." (PMID 41927527, 2026).
pancreatic ductal adenocarcinoma (1 paper, 2021). An infiltrating adenocarcinoma that arises from the epithelial cells of the pancreas. "Low expression of gene IGFBP7 was believed to be associated with poor outcome of pancreatic ductal adenocarcinoma." (PMID 34055623, 2021).
papillary thyroid carcinoma (1 paper, 2019). "Notably, classical papillary thyroid carcinoma (CPTC) tissues showed much strong IGFBP7 immunostaining, whereas follicular papillary thyroid carcinoma (FVPTC) tissues hardly showed IGFBP7 expression." (PMID 31183073, 2019).
peripheral arterial disease (1 paper, 2022). A disorder of the arteries supplying the upper and lower extremity and the visceral organs. "Patients with multilevel peripheral artery disease presented significantly higher IGFBP-7 concentrations than patients with aortoiliac occlusive disease—median 1.18 ng/mL (IQR 0.48–2.23) vs. 1.42 ng/mL (0.71–2.63), p = 0.035." (PMID 35625639, 2022).
pilocytic astrocytoma (1 paper, 2015). Pilocytic astrocytoma is a rare subtype of low-grade glioma of the central nervous system characterized by a well circumscribed, often cystic, brain tumor with a discrete mural nodule and long, hair-like projections that extend from the neoplastic astrocytes. "In pilocytic astrocytomas, we observed up-regulation of IGFBP7 and CEBPB, both of which are major transcriptional inducers of SASP-related genes." (PMID 26682910, 2015).
Pleural effusion (1 paper, 2019). The presence of an excessive amount of fluid in the pleural cavity. "The mean mRNA value of IGFBP7 expression in cancer cells isolated from treatment-naïve pleural effusions (n = 8) (0.114 ± 0.059) was significantly lower than that after acquired resistance to EGFR-TKI treatment (n = 16) (1.18 ± 0.412; p = 0.0212, by Student’s t-test)." (PMID 30609749, 2019).
preeclampsia (1 paper, 2025). Preeclampsia is a hypertensive disorder of pregnancy that is characterized by new-onset hypertension with proteinuria presenting after 20 weeks of gestation, and depending on mild or severe forms may initially present with severe headache, visual disturbances, and hyperreflexia. "Although late-onset preeclampsia is not as strongly associated with placental vascular dysfunction as early-onset preeclampsia, genes such as CP, IGFBP7, CDH13, ROBO1, UNC5C, NRXN3, and ITGA1 suggest subtle changes in angiogenic pathways." (PMID 41444673, 2025). "Similarly, the differential expression of vascular regulators such as IGFBP7 and CDH13 points to sex-specific differences in angiogenic regulation, a key aspect of placental development and preeclampsia pathophysiology." (PMID 41444673, 2025).
pyometra (1 paper, 2026). "This prospective cross-sectional blinded study evaluated whether urinary TIMP-2 and IGFBP7 reflect histopathological renal injury severity in 27 clinically non-azotemic female dogs with pyometra and systemic inflammatory response syndrome (SIRS)." (PMID 41884299, 2026).
sarcopenia (1 paper, 2024). Progressive decline in muscle mass due to aging which results in decreased functional capacity of muscles. "Elevated levels of IGF-1, IGF-1R, IGFBP-3, and IGFBP-7 within the IGF family are associated with a decreased risk of sarcopenia, indicating a causal associated with sarcopenia." (PMID 39507055, 2024). "As a result, we successfully identified a causal effect between IGF family members and sarcopenia, with higher levels of IGF-1, IGF-1R, IGFBP-3, and IGFBP-7 being associated with a reduced risk of sarcopenia." (PMID 39507055, 2024). "This study reveals that IGFBP-7 may have a positive impact on appendicular lean mass in limbs and could potentially reduce the risk of sarcopenia." (PMID 39507055, 2024). "In addition to IGF-1, within the IGF family, we found that IGF-1R increased whole body fat-free mass, and IGFBP-3 and IGFBP-7 increased appendicular lean mass, and improved muscle mass and muscle bulk, demonstrating that high IGF-1R, IGFBP-3, and IGFBP-7 levels may reduce the risk of sarcopenia." (PMID 39507055, 2024). "Further investigation is necessary to determine whether IGFBP-7 can serve as a biomarker for sarcopenia in the future." (PMID 39507055, 2024).
serous ovarian carcinomas (1 paper, 2015). "The aim of the present study was to investigate the role of IGFBP7 in high-grade serous ovarian carcinomas (HGSC), the most common type of EOC." (PMID 25886299, 2015). "We analysed IGFBP7 gene expression in 11 normal ovarian surface epithelial cells (NOSE), 79 high-grade serous ovarian carcinomas (HGSC), and seven EOC cell lines using a custom gene expression array platform." (PMID 25886299, 2015).
skin inflammation (1 paper, 2023). "This subset actively responded to psoriatic-related cytokine signaling, secreted IGFBP7, damaged the endothelial glycocalyx, exposed the adhesion molecules underneath, and prepared the endothelium for immune-cell adhesion and transmigration, thus aggravating skin inflammation." (PMID 36917196, 2023).
systolic heart failure (1 paper, 2016). Heart failure caused by abnormal myocardial contraction during systole leading to defective cardiac emptying. "Previous studies demonstrated the prognostic value of IGFBP-7 and IGF-1 among patients with systolic heart failure (HF)." (PMID 27769173, 2016).
Thyroid adenoma (1 paper, 2019). The presence of a adenoma of the thyroid gland. "Positive expression of IGFBP7 was detected in 66.7% of thyroid adenoma tissues and 65.0% of PTC tissues, but IGFBP7 was detectable only in 13.4% of FTC and 12.5% of ATC tissues." (PMID 31183073, 2019).
tongue tumor (1 paper, 2015). "Subsequently, 47 oral tongue tumor lesions were also performed to analyze the IGFBP-7 methylation status by MS-MSP." (PMID 25880247, 2015).
triple-negative breast carcinoma (1 paper, 2020). An invasive breast carcinoma which is negative for expression of estrogen receptor (ER), progesterone receptor (PR), and human epidermal growth factor receptor 2 (HER2). "It is demonstrated that insulin-like growth factor binding protein 7 (IGFBP7) induced the G1/G2 cell cycle arrest and senescence to inhibit growth of triple-negative breast cancer cells both in vitro and in mice." (PMID 31968672, 2020).
viral infection (1 paper, 2021). "The lack of renal TIMP-2, IGFBP7 and NGAL upregulation is not likely to be directly related to viral infection." (PMID 34112226, 2021).
vitiligo (1 paper, 2013). Generalized well circumscribed patches of leukoderma that are generally distributed over symmetric body locations and is due to autoimmune destruction of melanocytes. "Moreover, vitiligo melanocytes produced many biologically active proteins among the senescence-associated secretory phenotype (SAPS), such as interleukin-6 (IL-6), matrix metallo proteinase-3 (MMP3), cyclooxygenase-2 (Cox-2), insulin-like growth factor-binding protein-3 and 7 (IGFBP3, IGFBP7)." (PMID 23555779, 2013).
tumor (188 papers, 2007 to 2026). "RESULTS: Our findings revealed a progressive decrease in both IGFBP7 expression and secretion by tumor endothelial cells during inflammation-associated colorectal tumorigenesis." (PMID 41692778, 2026). "Functional annotation showed that IGFBP7 is closely associated with immune and inflammatory pathways, suggesting its importance in shaping the tumour immune landscape." (PMID 39788916, 2025). "Specifically, IGFBP7 has been shown to augment tumor-associated macrophage (TAM) infiltration, thereby promoting GC advancement, through the activation of the FGF2/FGFR1/PI3K/AKT signaling axis." (PMID 40485724, 2025). "In particular, IGFBP7 is implicated in cell adhesion and tumor cell proliferation processes, with its N-terminal fragments post-degradation retaining cell membrane adhesion properties." (PMID 39081862, 2024). "Conversely, treating tumor-bearing mice with a neutralizing antibody against CD93 that blocks its interaction with IGFBP7 was associated with vascular normalization." (PMID 38441970, 2024). "Recent research has shown that IGFBP7 promotes the polarization of tumour‐associated macrophages (TAMs) via the FGF2/FGFR1/PI3K/AKT axis, thereby facilitating the progression of GC." (PMID 39351597, 2024). "Exogenous recombinant IGFBP7 treatment in macrophages and GC cells further identified that IGFBP7 promotes tumor associated macrophage (TAM) polarization via FGF2/FGFR1/PI3K/AKT axis." (PMID 36681667, 2023). "The results suggest that high expression of IGFBP7 protein and mRNA is significantly associated with tumor progression and poor survival rate in GC." (PMID 37568781, 2023). "Tumor research mainly focused on those tumor related genes with overexpression, therefore, we will further explore the diagnostic value of IGFBP7 in this following study." (PMID 37304887, 2023). "IGFBP7 was positively associated with immunomodulators and promoted tumor-infiltrating lymphocyte trafficking into the tumor microenvironment." (PMID 35812369, 2022). "TIMP-2 is a 21 kDa protein with anti-apoptotic and pro-proliferative properties, while IGFBP7 is a 29 kDa protein which acts as an IGF-1 receptor antagonist that causes tumor suppression and regulates cellular aging by inhibiting kinase signaling." (PMID 36091391, 2022). "Several studies have demonstrated that IGFBP7 is typically overexpressed in tumor-associated endothelial cells relative to normal vascular endothelial cells." (PMID 35812369, 2022). "Early work on epithelial CRC cell lines found IGFBP7 expression is associated with tumour suppression." (PMID 34874125, 2022). "Both low IGFBP7 protein levels and mRNA expression were associated with less aggressive tumor characteristics." (PMID 34606580, 2021). "A previous small Swedish study reported associations between low IGFBP7 levels and more aggressive tumor characteristics." (PMID 34606580, 2021). "TIMER analysis indicated that the mRNA level of IGFBP7 was strongly correlated with genes related to various infiltrating immune cells in GC, especially with gene markers of tumor associated macrophages (TAMs)." (PMID 33531979, 2021). "The salient finding of this study is the association of urinary IGFBP-7 with renal impairment and tumor burden (marked by FLCs, albumin, β2-microglobulin)." (PMID 34946293, 2021). "The majority of the associations between IGFBP7 and tumor characteristics went in the same direction for protein and mRNA expression, except PR." (PMID 34606580, 2021). "They showed that the IGFBP7 expression in tumor-associated endothelium is much higher than in healthy endothelial cells." (PMID 32500027, 2020). "IGFBP7 expression in tumor-associated fibroblasts can also stimulate colony formation when neoplastic epithelial cells are co-cultured with IGFBP7-expressing cancer-associated fibroblasts by secondary (paracrine) tumor-stroma interactions." (PMID 32500027, 2020).